IL24 (interleukin 24)
Diseases named in the same sentence as IL24 in open-access papers (continued):
Sharing a sentence is not in itself a finding about the gene and the disease.
autoimmune disease (11 papers, 2016 to 2025). A disorder resulting from loss of function or tissue destruction of an organ or multiple organs, arising from humoral or cellular immune responses of the individual to their own tissue constituents. "Despite its regulatory properties affecting T-cell functions, IL-24 is susceptible to some autoimmune diseases." (PMID 36233291, 2022). "IL-24 is a proinflammatory cytokine associated with tissue inflammation and autoimmune diseases." (PMID 38737586, 2024). "IL-24 is a member of the IL-10 family of cytokines and is expressed by monocytes and T lymphocytes (mainly Th2), which has proinflammatory and proapoptotic effects and is associated with inflammation and autoimmune diseases." (PMID 36806964, 2023). "Taken together, IL-24 in differentiated Th17 cells has a role in regulating the pathogenic Th17 response, and may participate in the resolution of tissue inflammation and autoimmune diseases." (PMID 35054813, 2022). "However, our recent study highlighted the tolerogenic properties of IL-24 in regulating CNS autoimmune diseases, showing that mice deficient in IL-24 were more susceptible to EAU and experimental autoimmune encephalomyelitis (EAE)." (PMID 36233291, 2022). "In this section, we discuss the role of IL-24 in the regulation of various immune cells, which may be implicated in the pathogenesis of inflammatory and autoimmune diseases." (PMID 35054813, 2022). "We previously reported that IL-24−/− mice were less susceptible to EAE and EAU, suggesting that IL-24 may serve as a novel therapeutic treatment for T cell-mediated autoimmune diseases." (PMID 36233291, 2022). "We and others have already demonstrated the therapeutic utility of Interleukin 24 as an anticancer therapy and in autoimmune diseases and inflammation." (PMID 37444474, 2023). "An increase in the expression levels of IL-24 is connected to autoimmune diseases, such as psoriasis, inflammatory bowel disease, and rheumatoid arthritis." (PMID 37484532, 2023). "Human interleukin 24 (IL-24) is a multifunctional cytokine that represents an important target for autoimmune diseases and cancer." (PMID 37484532, 2023). "In this review, we discuss the immunoregulatory functions of IL-24 and its roles in autoimmune diseases." (PMID 35054813, 2022). "As such, greater effort should be made to characterize the complex role of IL-24 in inflammatory and autoimmune diseases." (PMID 35054813, 2022). "In this review, we highlight the recent findings regarding the function of IL-24 in the regulation of immune cells and its role in autoimmune diseases." (PMID 35054813, 2022). "Because of the high expression of these receptors in epithelial cells, the role of IL-24 in tissue inflammation and autoimmune diseases has been studied intensively." (PMID 35054813, 2022). "Therefore, SOCS proteins play an important downstream role in the IL-24 signal transduction pathway for various inflammatory and autoimmune diseases." (PMID 37444474, 2023). "Little is known about the role of IL-24 in the context of autoimmune diseases in CNS." (PMID 35054813, 2022). "In accordance with what has been observed with IL-24, the combination of immunosuppression and anti-inflammatory properties makes Sig1R ligands attractive molecules for therapeutic applications like in autoimmune diseases where both immune and inflammatory processes are involved." (PMID 27271601, 2016). "These discoveries open a new therapeutic possibility for various inflammatory and autoimmune diseases, such as multiple sclerosis, rheumatoid arthritis, Crohn’s disease, and autoimmune uveitis; increased IL-24 expression in addition to IL-17A could be a possible therapeutic strategy." (PMID 37444474, 2023). "Therefore, we hypothesized that IL-24 has a complex role in regulating different autoimmune diseases and may potentially suppress autoimmune uveitis by regulating autoreactive T cells and RPE cells." (PMID 36233291, 2022).
autoimmune disease (continued). "Therefore, a decrease in the secretion of IL24 by MSCs as a result of Vadadustat treatment seems to be a beneficial effect when considering the use of Vadadustat preconditioned MSCs in the treatment of patients with autoimmune diseases." (PMID 33139632, 2020). "Although IL-19 and IL-24 have been studied extensively in other autoimmune diseases, their exact role in IBD is not entirely clear." (PMID 39007024, 2024). "IL-17A inhibits the Th17 cytokine program via negative feedback regulation through autocrine induction of IL-24, preventing the Th17 pathogenicity in autoimmune diseases." (PMID 37444474, 2023). "However, IL-24′s potential as a new therapeutic candidate for treating autoimmune diseases has not been fully explored." (PMID 36233291, 2022).
ovarian carcinoma (11 papers, 2007 to 2025). A malignant neoplasm originating from the surface ovarian epithelium. "Several reports using an adenovirus encoding the mda-7/IL-24 gene (Ad-mda-7) show its profound and selective anticancer activity in animal models including a report of selectively induced cell death of ovarian cancer cells that results in suppression of tumor growth in vivo." (PMID 21931671, 2011). "IL‐24‐mediated apoptotic cell death in ovarian cancer cells was found to be a consequence of the activation of transcription factors c‐Jun and ATF2, which, in turn, stimulated Fas/FasL signaling, ultimately converging on NF‐κB and promoting cellular apoptosis." (PMID 40338095, 2025). "In the aggregate, our in vitro findings warrant further preclinical studies of CRAd-IL24 to test its efficacy in murine ovarian cancer models to establish its potential utility for the virotherapy treatment of primary and advanced neoplastic diseases." (PMID 27349517, 2016). "This recognition now allows us to determine the full utilities that derive from our CRAd-IL24 agent in preclinical studies employing immunocompetent syngenic murine ovarian cancer model." (PMID 27349517, 2016). "In CAOV-3 and SW626 ovarian cancer cell lines mda-7/IL-24 is also strongly induced (maximum of 77-fold induction in CAOV-3 cells)." (PMID 21931671, 2011). "As NSAIDs induce mda-7/IL-24 expression in ovarian cancer cells, we evaluated changes in GADD45 α and γ gene expression." (PMID 21931671, 2011). "A broad panel of NSAIDs was tested for their abilities to induce apoptosis and mda-7/IL-24 gene expression in four ovarian cancer cell lines, SKOV-3, CAOV-3, SW626 and 36M2." (PMID 21931671, 2011). "We also identified Naproxen and Ebselen as moderate inducers of apoptosis and mda-7/IL-24 expression in ovarian cancer cells." (PMID 21931671, 2011). "Here, we demonstrate that Sulindac Sulfide and Diclofenac are the most potent NSAIDs that induce ovarian cancer apoptosis via mda-7/IL-24 expression and also reduce tumor growth in vivo." (PMID 21931671, 2011). "In this report we evaluated various structurally different NSAIDs for their efficacies to induce apoptosis and mda-7/IL-24 expression in ovarian cancer cells." (PMID 21931671, 2011). "In this context, our findings that NSAIDs with anti-cancer activity induce high levels of mda-7/IL-24 in ovarian cancer cells provide a new therapeutic strategy to enhance mda-7/IL-24 levels on a systemic level." (PMID 21931671, 2011). "Recent in vitro studies from our laboratory and those performed by others showed that mda-7/IL-24 can suppress ovarian cancer cell growth in vitro and is dependent on the Fas/FasL or stress activated p38 mitogen-activated protein kinase (MAPK) pathway." (PMID 17274815, 2007). "Our results show that treatment of ovarian cancer cells with mda-7/IL-24 results in growth suppression both in vitro and in vivo." (PMID 17274815, 2007). "In the present study, we investigated the antitumor activity of mda-7/IL-24 against human ovarian cancer cells both in vitro and in vivo." (PMID 17274815, 2007). "Although mda-7/IL-24 has displayed antitumor activity against ovarian cancer cells in vitro, the documented evidence of this activity in vivo is limited." (PMID 17274815, 2007). "The generated CRAd-IL24 and CRAd-IN4 were tested along with control CRAd vector to validate hypothesis that arming Ad5/3Δ24 with IL-24 or ING4 therapeutic payload may improve oncolytic CRAd potency following infection ovarian cancer cells in vitro and in vivo." (PMID 27349517, 2016). "In summary, our results strongly support the hypothesis that drug treatment regimens that lead to enhanced mda-7/IL-24 expression in cancer cells and block NF-κB may have significant efficacy against ovarian cancer." (PMID 21931671, 2011). "Moreover, several studies indicated that overexpression of mda-7/IL-24 by a recombinant adenovirus results in cancer cell apoptosis and therapeutic benefits in ovarian cancer." (PMID 21931671, 2011).
ovarian carcinoma (continued). "Ebselen and Naproxen induced apoptosis and mda-7/IL-24 expression in ovarian cancer cells and also synergized with the more potent NSAIDs, Diclofenac and Sulindac Sulfide, suggesting potential clinical utility in ovarian cancer therapy." (PMID 21931671, 2011). "We measured mRNA expression levels of mda-7/IL-24 mRNA in response to different NSAIDs in SKOV-3 cells by real time PCR analysis demonstrating that mda-7/IL-24 (maximum of 12-fold induction) expression is commonly induced by NSAIDs that promote apoptosis in ovarian cancer cells." (PMID 21931671, 2011). "Indeed, we have obtained a comprehensive overview of the consequences of a whole panel of NSAIDs on ovarian cancer cell survival by comparing their efficacies to induce apoptosis and mda-7/IL-24 expression." (PMID 21931671, 2011). "Lentiviral expression of siRNA against mda-7/IL-24 in ovarian cancer cells demonstrated that knockdown of mda-7/IL-24 reduces diclofenac-induced GADD45 α and γ gene expression indicating that GADD45α and γ induction is at least partially dependent on mda-7/IL-24 expression." (PMID 21931671, 2011). "Our results indicate that inhibition of NF-κB in combination with activation of mda-7/IL-24 expression may lead to a new combinatorial therapy for ovarian cancer." (PMID 21931671, 2011). "In the present study we investigated the antitumor activity of mda-7/IL-24 against human ovarian cancer cells and compared to normal ovarian epithelial cells in vitro and the mda-7-mediated growth inhibitory effects on human ovarian tumor xenograft mouse models in vivo." (PMID 17274815, 2007). "Based on these encouraging data we constructed Ad5/3∆24 CRAd derivatives armed with IL-24 or ING4 gene and tested their oncolytic potency in human ovarian cancer cell lines and immortalized normal ovarian surface epithelial cells." (PMID 27349517, 2016). "The generated CRAd-IL24 and CRAd-ING4 vectors were tested in ovarian cancer cell lines in vitro to compare their replication, yield, and cytotoxic effects with control CRAd Ad5/3∆24 lacking the therapeutic gene." (PMID 27349517, 2016). "Furthermore, IFNG, IL24, MTMR14, and RB1 were highly expressed in ovarian cancer than normal tissues." (PMID 33748162, 2021). "Moreover, CXCR4, IFNG, IL24, MTMR14, and RB1 all exhibited higher expression in ovarian cancer compared to normal specimens." (PMID 33748162, 2021). "To determine whether arming with IL-24 or ING4 therapeutic genes leads to improved oncolytic CRAd potency we tested cell viability and cytotoxicity following infection of normal and ovarian cancer (OvCa) cells." (PMID 27349517, 2016). "Overall, these studies revealed that oncolytic potency of CRAd-IL24 is significantly increased as compared to control CRAd and CRAd-ING4 thus, providing a strong rationale for further preclinical testing of CRAd-IL24 therapeutic utility against carcinoma of the ovary." (PMID 27349517, 2016). "Based on previous encouraging data using IL-24 gene to arm both Ad5-based and Ad5/3-based CTV CRAd we choose to test whether our Ad5/3Δ24 vector designed to express IL-24 could provide therapeutic benefit for oncolytic treatment of carcinoma of the ovary." (PMID 27349517, 2016).
rheumatoid arthritis (11 papers, 2010 to 2025). A chronic, systemic autoimmune disorder characterized by inflammation in the synovial membranes and articular surfaces. "Clearly, IL-24 is associated with RA diseases but more research is required to fully understand the biology of IL-24 in rheumatoid arthritis." (PMID 27271601, 2016). "IL-24 is highly expressed in rheumatoid arthritis and spondylarthritis, but its presence and role in IVDs and IVD-derived fibrochondrocytes is completely unclear." (PMID 37447201, 2023). "In the bootstrap resampling, we selected several important rheumatoid arthritis genes such as MMP genes (MMP1, MMP3), CCL genes (CCL3, CCL4, and CCL26), and IL genes (IL6, IL8, IL19, and IL24)." (PMID 31371761, 2019).
gastric cancer (10 papers, 2011 to 2025). A primary or metastatic malignant neoplasm involving the stomach. "The IL-20 cytokine IL-24 can induce apoptosis in gastric cancer cells and inhibits tumor angiogenesis in vivo in a chicken embryonic allantois model." (PMID 29967613, 2018). "We have reported that induction of mda-7/IL-24 by structurally different NSAIDs is crucial for apoptosis induction of breast, prostate, renal and stomach cancer cells." (PMID 21931671, 2011). "Restoring IL24 expression can inhibit gastric cancer cell growth and proliferation." (PMID 39850884, 2024). "Moreover, overexpression of IL-24 in the gastric cancer cell line SGC7901 sensitizes these cells to cisplatin, 5-fluorouracil, adriamycin, and methotrexate." (PMID 29967613, 2018). "Conversely, increased expression and secretion of IL-24, another member of the IL-20 subfamily, was evidenced in macrophages polarized into a pro-inflammatory phenotype that induces apoptosis in gastric cancer (GC) cells." (PMID 40806452, 2025). "GSVA analysis suggested that IL24 and JUND expression is significantly positively correlated with the metastasis process in gastric cancer." (PMID 39850884, 2024).
atopic dermatitis (8 papers, 2017 to 2026). "For example SDC-4 (syndecan-4) mRNA levels were increased in atopic dermatitis compared with normal skin samples and the inflammatory mediators IL-17, IL-20, IL-24, IL-31, and IL-33 were also elevated in atopic dermatitis." (PMID 29383128, 2017). "There is an upregulation of IL-24 expression in atopic dermatitis and in psoriatic epidermis, being a pivotal mediator in the development of both dermatoses and a key element in the immunological understanding of psoriasis-like features in atopic dermatitis skin." (PMID 35387041, 2021). "We found that WNT5A+/IL24+ signature genes were absent from healthy skin, weakly expressed in atopic dermatitis, but readily detectable in prurigo nodularis lesions." (PMID 38291032, 2024).
glioblastoma (8 papers, 2015 to 2025). The most malignant astrocytic tumor (WHO grade IV). "An additional follow‐up study from the same research group investigated the effects of a GST fusion protein containing IL‐24 in glioblastoma models." (PMID 40338095, 2025). "The present findings demonstrated that transduction of IL-24 inhibited cell proliferation and induced cell cycle arrest and cell apoptosis in glioblastoma." (PMID 37280571, 2023). "Transgenic inhibition of PERK abrogated both the increase in glioblastoma cell ceramides and apoptosis initiated by IL24." (PMID 37183938, 2023). "In summary, adenovirus expressing human IL-24 is able to significantly increase cytotoxicity and inhibit cell growth in the U87 glioblastoma cell line." (PMID 37280571, 2023). "In our research, we found that rutaecarpine, but not evodiamine and dehydroevodiamine, can upregulate the expression of IL24 by activating the AhR signaling pathway, thereby inhibiting the migration of glioblastoma." (PMID 34955744, 2021). "Meanwhile, we propose AhR and IL24 as composite targets for screening anti-glioblastoma migration compounds." (PMID 34955744, 2021). "Moreover, in U87 glioblastoma cells, in addition to apoptosis induced by IL24 an elevated expression of LC3‐II protein, suggestive of autophagy activation, was also observed." (PMID 40338095, 2025). "Therefore, in our study, the expression of IL-24 and the resulting increase in the level of p38 in glioblastoma cells can exert its antitumor effects." (PMID 37280571, 2023). "Human glioblastoma U87 cell line was exposed to a multiplicity of infections of Ad/IL-24." (PMID 37280571, 2023). "Our study demonstrates the antitumor effect of IL-24 on glioblastoma and may be a promising therapeutic approach for GBM cancer gene therapy." (PMID 37280571, 2023). "In conclusion, we found that rutaecarpine is a natural compound with AhR activation activity, which can inhibit the migration of U87 human glioblastoma cells by activating the AhR signaling pathway and inducing the expression of downstream tumor suppressor IL24." (PMID 34955744, 2021). "Another recent study revealed that IL‐24 administration increased the expression of the epithelial marker E‐Cadherin and suppressed Zeb1 in glioblastoma multiforme (GBM) cell lines, leading to increased sensitivity to temozolomide." (PMID 40338095, 2025). "Our study provides a new approach to the treatment of glioblastoma and establishes a theoretical basis for IL-24 as a potential therapeutic gene for GBM cancer gene therapy." (PMID 37280571, 2023). "IL-24 destabilized the stability of ZEB1 via increasing the expression of FBXO45 in human glioblastoma cells, contributing to inhibition of malignancy of glioblastoma." (PMID 38773471, 2024).
liver cancer (8 papers, 2015 to 2024). An epithelial or non-epithelial malignant neoplasm that arises from the liver. "Several studies have shown that IL-24 can selectively block proliferation by promoting G2/M arrest in many tumor cells, such as breast, lung, and liver cancer cells." (PMID 35915803, 2022). "In our study, luteolin can increase VV‐mediated IL‐24 gene expression in liver cancer cells in vitro and in vivo." (PMID 33274495, 2021). "The present investigation demonstrated that oncolytic VV harboring the IL‐24 gene, VV‐IL‐24, efficiently inhibited liver cancer cells viability." (PMID 33274495, 2021). "The aim of this study was to investigate the effects of regulation of IL‐24 by miR‐203a‐3p.1 on liver cancer cell proliferation and metastasis." (PMID 28781949, 2017). "In MHCC97‐H and HepG2 cells, the combination treatment of VV‐IL‐24 and luteolin upregulated IL‐24 gene expression more than VV‐IL‐24 or luteolin alone, suggesting that luteolin could increase VV‐IL‐24 expression in liver cancer cells." (PMID 33274495, 2021). "Therefore, our study aimed to prove whether oncolytic vaccinia virus (VV) that harbors IL‐24 (VV‐IL‐24) combine with luteolin exerts a synergistic inhibitory effect in liver cancer cells." (PMID 33274495, 2021).
colon carcinoma (7 papers, 2012 to 2025). "IL‐24, when used in combination with 5′‐fluorouracil and doxorubicin, increased the sensitivity of colon cancer cells to both drugs in in vitro model systems." (PMID 40338095, 2025). "This study evaluated the effects of IL-20, IL-22, and IL-24 in epithelial renewal using the LS174T human colon cancer epithelial cell line." (PMID 31311100, 2019). "Additionally, administration of IL‐24 reconfigured the TME (tumor microenvironment) in murine colon cancer models, with a higher percentage of CD45+ CD4+ and CD45+ CD8+ cells and a decrease in CD45+ CD4+ Foxp3+ cells, suggestive of a type I immune response." (PMID 40338095, 2025). "This was similar to the in vivo findings that administration of 50 μg recombinant IL-24 promoted CD4+ T cells response, especially increased IFN-γ production in colon cancer mouse model." (PMID 31921658, 2019). "Importantly, IL-24 also enhanced IFN-γ secretion by T cells and promoted cytotoxicity of CD8+ T cells in a colon cancer mouse model." (PMID 31921658, 2019).